TFEB (transcription factor EB)
Diseases named in the same sentence as TFEB in open-access papers (continued):
Sharing a sentence is not in itself a finding about the gene and the disease.
infection (continued). "Previous studies have shown that the depletion of TFEB induces the multiplication of pathogens by downregulating autophagy during infection." (PMID 35873583, 2022). "The larger HLH-30/TFEB regulon implies that during infection signals in addition to NHR-49/PPAR-α activation contribute to HLH-30/TFEB regulation." (PMID 33978570, 2021). "In contrast, in infected hlh-30/TFEB mutants compared with wild type, nhr-49/PPARA expression was lower, indicating that HLH-30/TFEB contributes to nhr-49/PPARA expression during infection." (PMID 33978570, 2021). "Several additional conditions, such as infection, inflammation, physical exercise, endoplasmic reticulum stress, and mitochondrial damage, also promote TFEB nuclear translocation, highlighting the complexity of TFEB regulation." (PMID 33459519, 2021). "Conversely, in nhr-49/PPARA null mutants hlh-30/TFEB baseline expression was higher than in wild type, yet its induction by infection was abrogated." (PMID 33978570, 2021). "The transcriptional protein NR1D1 plays a key role in infection and inflammation and its activation led to the modulation in the expression of transcription factor EB (TFEB)." (PMID 34070995, 2021). "Both the starvation response and the infection-specific signature were largely dependent on HLH-30/TFEB, highlighting its key role as a transcriptional integrator of organismal stress during infection." (PMID 33978570, 2021). "Altogether, these results showed that HLH-30/TFEB is crucial for both the starvation and the infection-specific responses, and hinted at an HLH-30/TFEB-independent pathway for the induction of six infection-specific genes." (PMID 33978570, 2021). "In the present work, Mabs-R infection of macrophages markedly decreased the expression and nuclear translocation of TFEB." (PMID 34447358, 2021). "HLH-30/TFEB was shown to be important for gene induction during dietary challenge and during infection." (PMID 33978570, 2021). "This indicated that nhr-49/PPARA is required for increased expression of hlh-30/TFEB during infection." (PMID 33978570, 2021). "To assess the relevance of HLH-30/TFEB to the infection-specific signature, we compared starved and infected hlh-30/TFEB loss-of-function mutants by RNA-seq." (PMID 33978570, 2021). "As the most highly induced infection-specific gene in hlh-30/TFEB mutants, fmo-2/FMO5 attracted our attention." (PMID 33978570, 2021). "The activation of lipid catabolism via transcriptional activity of transcription factor EB/peroxisome proliferator-activated receptor α (TFEB/PPARα) potentiates macrophage response to infection." (PMID 32781626, 2020). "Several lines of evidence suggest that the activation of TFEB early during infection is evolutionarily conserved, positioning this molecule as a key component of host defense." (PMID 32423042, 2020). "We compared the intracellular translocation of TFEB in BMDMs after Mabc infection between Ppara+/+ and Ppara-/- BMDMs." (PMID 32155958, 2020). "We found that TFEB nuclear translocation was significantly increased in Ppara+/+ BMDMs, but markedly decreased in Ppara-/- BMDMs, after 30 min of Mabc infection." (PMID 32155958, 2020). "As expected, TFEB transcription was increased by Myr, suggesting that lipid catabolism and autophagy are enhanced even under infection conditions." (PMID 32781626, 2020). "Future work involving infection studies would be needed to determine if TFEB is a physiological target of SetA." (PMID 32622269, 2020). "The expression level of TFEB was positive-regulated by the inhibitors upon the infection of Salmonella and S. aureus." (PMID 33324360, 2020). "The expression and activation of TFEB were enhanced early under the infection of S. aureus, which was followed by shrinkage to weaken lysosomal functions due to the delayed activation of ERK, mTOR, and STAT3." (PMID 33324360, 2020).
infection (continued). "We have verified the great role of TFEB in the defense of bacteria, and explored critical mechanisms to regulate the expression and activity of TFEB during the infection of Salmonella and S. aureus." (PMID 33324360, 2020). "TFEB mRNA levels were significantly knocked down at 48 h and 72 h after infection, as compared to mock-infected controls and the efficiency of TFEB knockdown was 65% and 60%, respectively (n = 6)." (PMID 30360758, 2018). "A. baumannii cellular infection increased the expression of TFEB in a time-dependent manner after 6 h by ≈83%." (PMID 29600279, 2018). "Conversely, although Nef deleted HIV similarly induces TFEB dephosphorylation and nuclear localization, and increases autophagy, these levels remain elevated during continued productive infection." (PMID 26115100, 2015). "The dephosphorylation and activation of TFEB lasted until at least 72 h post-infection and by 5 d post-infection, although levels were elevated, TFEB was localized predominantly to the cytoplasmic fraction." (PMID 26115100, 2015). "Earlier, at 24 h post-infection, TFEB-expressing cells (∼10–20% of myotubes) showed a striking relocation of enlarged lysosomes toward the plasma membrane; images taken at this time point provide a snapshot of the process of lysosomal secretion (top)." (PMID 23606558, 2013). "At later infection times, however, TFEB and TFE3 degradation or inactivation may avert autophagy-mediated clearance of assembled viral particles and even facilitate virus dissemination by inducing cell death." (PMID 40195022, 2025). "However, in the later stages of infection, TFEB is cleaved, resulting in inhibition of autophagic flux, facilitating the autophagosome-mediated nonlytic release of EV-D68." (PMID 39398108, 2024). "TFEB has been shown to transcriptionally regulate cytokine expression during infection; thus, we next asked whether TFEB cytosolic localization affects the inflammatory outcome during S. Typhimurium infection." (PMID 38263327, 2024). "However, despite cleaving TFEB at an identical site, TFEB remains largely cytosolic during EV-D68 infection." (PMID 39398108, 2024). "Therefore, epithelial TFEB contributes to the production of anti-bacterial peptides to fight infection." (PMID 38711975, 2024). "In addition, S. Typhimurium prevented TFEB mitochondrial translocation at later time point of infection, which correlates with our previous findings that it activates mTOR and thereby inhibits autophagy." (PMID 38263327, 2024). "Therefore, how TFEB is regulated under the infection of Salmonella and what the distinctive functions of TFEB are in colonic epithelial cells are still ambiguous." (PMID 38711975, 2024). "In HeLa WT cells, TFEB predominantly localized to the nucleus during infection." (PMID 39572689, 2024). "Thus, we decided to investigate a role for TFEB during infection of enterovirus D68 (EV-D68), a related picornavirus and primary causative agent of the childhood paralysis disease acute flaccid myelitis." (PMID 39398108, 2024). "Therefore, nuclear translocation of TFEB is associated with IFITM2/3 degradation and increased cellular susceptibility to SARS-CoV-2 Spike-mediated infection." (PMID 33880473, 2022). "Thus, under nutrient-rich conditions, TFEB is located in the cytoplasm under basal cellular conditions and translocates to the nucleus in response to starvation, lysosomal stress, pathogen infections, ER stress, and exercise to promote organismal homeostasis." (PMID 36231114, 2022). "Therefore, nuclear translocation of TFEB was associated with IFITM2/-3 degradation and increased cellular susceptibility to SARS-CoV-2 spike–mediated infection." (PMID 36264642, 2022). "TFEB belongs to the MiT family of transcription factors, which in mammals and C. elegans controls the transcription of autophagy and lysosomal genes in response to nutritional stress in addition to infection." (PMID 33978570, 2021).
infection (continued). "After infection by the bacterium, host TFEB is activated which results in activation of lysosomal biogenesis and autophagy that could promote the death of host cells." (PMID 32528902, 2020). "Moreover, HLH-30, the TFEB ortholog of Caenorhabditis elegans, plays an important role in promoting survival of the nematode during infection by the bacterium." (PMID 32528902, 2020). "The results showed that VX-765 could promote the TFEB to transfer into the nucleus under infection of Salmonella, while S31-201, rapamycin and ERKi could dramatically increase the nuclear TFEB upon infection of S. aureus." (PMID 33324360, 2020). "Additionally, using the C. elegans infection model by A. baumannii, we have showed that the TFEB orthologue HLH-30 was required for survival of the nematode to infection, although HLH-30 translocation in the nucleus of C. elegans is very weak." (PMID 29600279, 2018). "Additionally, using the C. elegans infection model by A. baumannii, the TFEB orthologue HLH-30 was required for survival of the nematode to infection, although nuclear translocation of HLH-30 was not required." (PMID 29600279, 2018). "Collectively, these data suggest a hypothetical model whereby infection triggers TFEB activation, which could induce the autophagosome-lysosome system to promote the intracellular trafficking and persistence of A. baumannii within cells." (PMID 29600279, 2018). "However, once HIV establishes a productive infection, TFEB phosphorylation and cytoplasmic sequestration are increased resulting in decreased autophagy markers." (PMID 26115100, 2015). "However, by 6 d post-infection, this effect had dissipated and TFEB localization was again similar to the mock-infected controls." (PMID 26115100, 2015). "As permissive HIV infection is not required for the induction of autophagy, we investigated whether productive infection was required for the dephosphorylation and nuclear translocation of TFEB at the early time points." (PMID 26115100, 2015). "However, once HIV infection is established, phosphorylation and cytoplasmic sequestration of TFEB as well as autophagy revert to pre-infection levels." (PMID 26115100, 2015). "Through in vivo and in vitro experiments, we confirmed that SESN2 could inhibit this “infection” through the reduction of exosome release by promoting autophagic degradation; Rab-7a-mediated autophagosome and lysosome fusion and TFEB-mediated lysosomal function repair may play roles in this process." (PMID 40612680, 2025). "Interestingly, TFEB is regulated by external stimuli such as infection." (PMID 41129589, 2025). "Furthermore, infection with Salmonella has a similar effect on the TFEB translocation." (PMID 38711975, 2024). "Thus, TFEB is useful to the virus early in infection but cleaved late in infection." (PMID 39398108, 2024). "TFEB regulates inflammation and immunity upon infection in macrophages in a transcriptional program conserved in the nematode Caenorhabditis elegans with recent data indicating mitochondrial metabolism may contribute to the effector function of TFEB activated macrophages." (PMID 38263327, 2024). "Thus, although published precedent supports NHR-42 as a functional homolog of NR1D1, the regulation of NHR-42/NR1D1 by HLH-30/TFEB during infection is a novel and important interaction that could be exploited for therapeutic purposes." (PMID 36860863, 2023). "Thus, it would be the future target to compare the different aspects between Mabs-R and Mabs-S in terms of Rufomycin 4–7-induced autophagy and understand how Rufomycin 4–7 activates TFEB nuclear translocation and upregulates the TFEB-related gene subsets under Mabs infection." (PMID 34447358, 2021). "However, it is largely unknown how TFEB expression and nuclear translocation are modulated during Mabs-R infection." (PMID 34447358, 2021). "Thus, HLH-30/TFEB could potentially integrate organismal stress, metabolism, and pathogen recognition to elicit coordinated host responses to infection." (PMID 33978570, 2021).
infection (continued). "In the present study, we found that loss of HLH-30/TFEB almost completely abrogated differential gene expression between starvation and infection – implicating HLH-30/TFEB not just in a hypothetical overlapping response but also in each of these two distinct signatures." (PMID 33978570, 2021). "The specific contribution of TFEB, TFE3, MITF, and their temporal regulation during infection requires further investigation." (PMID 40435199, 2025). "The functional effect of IBV infection on TFEB/TFE3 was first assessed by isolating cytoplasmic and nuclear proteins from IBV-infected HeLa cells at different time points post-infection." (PMID 41450945, 2025). "Following infection with S. aureus, the activation of STAT3 occurs later than other signaling pathways, such as ERK and mTOR, leading to the delayed suppression of TFEB, a key regulator of lysosomal biogenesis and function." (PMID 40936092, 2025). "In addition to changes in nutrient status, TFEB is activated by a variety of cellular stresses, including lysosomal damage, mitochondrial damage, infection, endoplasmic reticulum (ER) stress, DNA damage, proteasome inhibition, oxidative stress, and physical exercise." (PMID 40880129, 2025). "TFEB expression is modulated by the activation of the transcriptional protein NR1D1, which is important in infection and inflammation." (PMID 38138088, 2023). "We found decreased phospho-TFEB and increased TFEB with LC3-II levels in mTOR inhibited condition of NCoR1 KD mo-MΦ at 2 h and 24 h post H37Rv infection." (PMID 37590294, 2023). "For instance, infection of macrophages with Mycobacterium tuberculosis or HIV stimulates IRGM and GABARAP to inhibit mTORC1‐mediated phosphorylation of TFEB, driving its nuclear translocation." (PMID 37728021, 2023). "They demonstrated that infection with the coronaviruses OC43 and 229E promote TFEB degradation by activating the PAK2 kinase that phosphorylates TFEB and primes it for ubiquitin-driven degradation mediated by the E3 ubiquitin ligase subunit DCAF7." (PMID 35562967, 2022). "Because hlh-30/TFEB and nhr-49/PPARA contributed to both infection-specific fmo-2/FMO5 induction and each other’s expression, we examined their genetic interactions." (PMID 33978570, 2021). "The roles of TFEB and TFE3 in lysosomal regulation for cellular adaptation under a variety of acute stress conditions such as nutrient deprivation and pathogen infection are well documented." (PMID 33932147, 2021). "Following infection with M. tuberculosis, PPAR-α-/- bone marrow-derived macrophages decrease the activation of the transcription factor EB (TFEB), a responsible factor for the regulation of autophagy, and increase lipid droplet formation." (PMID 34299217, 2021). "During infection, NHR-49/PPAR-α appeared to be essential for fmo-2/FMO5 expression in the whole animal, while hlh-30/TFEB was partially dispensable in the intestine and pharynx." (PMID 33978570, 2021). "We found that if TFEB was knocked down, the ATP6V0D2 was obviously down-regulated on infection of bacteria alone or combined with inhibitors." (PMID 33324360, 2020). "Other stressors, such as ER stress, pathogen infection and oxidative stress, result in TFE3 and TFEB activation despite high mTORC1 activity." (PMID 30520728, 2018). "Once HIV establishes a productive infection, Nef inhibits autophagy by binding BECN1 resulting in TFEB phosphorylation and cytosolic sequestration." (PMID 26115100, 2015). "Once HIV establishes a productive infection, Nef binds BECN1 resulting in MTOR activation, TFEB phosphorylation and cytosolic sequestration and the inhibition of autophagy." (PMID 26115100, 2015). "During permissive infection, Nef binds BECN1 resulting in mammalian target of rapamycin (MTOR) activation, TFEB phosphorylation and cytosolic sequestration, and the inhibition of autophagy." (PMID 26115100, 2015).
infection (continued). "Although our study has concentrated on boosting TFEB levels during infection, the efficacy of DCAF7 inhibitors to modulate TFEB activity under basal conditions suggests potential application of this approach for other, noninfectious conditions associated with impaired autolysosomal activity." (PMID 40465712, 2025). "The transcription factors TFEB and TFE3 translocate from the cytosol to the nucleus in response to a wide variety of stress conditions, including nutrient deprivation, organelle damage, oxidative stress, and pathogen infection." (PMID 40195022, 2025). "Some viruses may benefit from inducing TFEB and TFE3 activation at early infection times as a way to prevent cell death and enhance production of autophagosomal membranes that they require for replication." (PMID 40195022, 2025). "In FNIP1/2-DKO cells where the FLCN-FNIP complex cannot form, TFEB is localized in the cell nucleus, regardless of infection status, as expected." (PMID 39572689, 2024). "Meanwhile, nuclear localization rates of TFEB were notably increased at 1, 3 h and declined at 5 h with the infection of S. aureus, but not obviously in Salmonella group." (PMID 33324360, 2020). "Indeed, overexpression of TFEB was found to decrease CCV size and bacterial replication during infection." (PMID 33251162, 2020). "TFEB immunostaining showed that in noninfected control cells, most of TFEB staining is found in the cytoplasm, while 2 h after infection, TFEB is robustly translocated into the nucleus." (PMID 29600279, 2018). "Collectively, these data suggest that exposure of macrophages to HIV induces TLR8-dependent TFEB dephosphorylation and nuclear translocation that induces autophagy, and that this is not dependent upon a productive infection." (PMID 26115100, 2015). "We found that in the absence of Nef the HIV-induced TFEB nuclear translocation and induction of autophagy was present at 10 d post-infection." (PMID 26115100, 2015). "Treatment with AT-2-inactivated purified HIV led to the dephosphorylation and nuclear localization of TFEB by 24 h indicating that productive infection was not necessary." (PMID 26115100, 2015). "Both infectious HIV and AT-2-inactivated HIV increased the transcription of ATG9B, UVRAG, and MCOLN1 suggesting activation of TFEB by HIV does not require productive infection." (PMID 26115100, 2015). "In relation to infection, this unique pathway was first identified in a Salmonella infection model, where GABARAPs targeting the Salmonella-containing vacuoles (SCVs) effectively sequestered FLCN, leading to the activation of TFEB, which is considered inducing catabolic activities." (PMID 39572689, 2024). "Consequently, during infection, lack of TFEB specifically in the mitochondria exacerbates the expression of pro-inflammatory cytokines, contributing to innate immune pathogenesis." (PMID 38263327, 2024). "Moreover, we identified six genes that were specifically induced during infection even in the absence of HLH-30/TFEB, potentially revealing an alternative transcriptional host response signaling pathway." (PMID 33978570, 2021). "In addition, using the Caenorhabditis elegans infection model by A. baumannii, the TFEB orthologue HLH-30 was required for survival of the nematode to infection, although nuclear translocation of HLH-30 was not required." (PMID 29600279, 2018). "To address the role of TFEB in the context of an infective process in a complete organism and because TFEB and its C. elegans orthologue HLH-30 are both regulated by infection, we hypothesized that HLH-30 might also be required for C. elegans to cope with A. baumannii infection." (PMID 29600279, 2018). "Hence, we explored TFEB's role in autophagy- and xenophagy-impaired phagocytosis by knocking down TFEB expression in RAW cells followed by pretreatment with fisetin (20 μM) for 8 hrs and infection with PA01-GFP at an MOI of 10 for 3 hrs." (PMID 29445254, 2017).